MYH9 (myosin heavy chain 9)
Diseases named in the same sentence as MYH9 in open-access papers (continued):
Sharing a sentence is not in itself a finding about the gene and the disease.
Nephropathy (continued). "With regard to the most prevalent MYH9-related disease (MYH9-RD), the affected subjects can manifest sensorineural deafness, nephropathy, juvenile cataracts, and elevation of liver enzymes." (PMID 32079152, 2020). "Cases with gene variants in LMX1B (nail–patella syndrome), PAX2 (renal coloboma syndrome), or MYH9 (MYH9 nephropathy) also show lamellation of the GBM, so they should be included in the gene list." (PMID 30128941, 2019). "Thepathogenesis of MYH9-nephropathy is not completely understood.NMMHC-IIA is an important component of podocyte foot process." (PMID 29782633, 2018). "It has been reported that the strongest kidney disease association was mapped to the region of introns 13–15 by genotyping 79 MYH9 SNPs in a total of 2496 cases (FSGS, HIV-associated nephropathy, and ESRD attributed to hypertension) and healthy controls." (PMID 29862302, 2018). "Individuals affected by a MYH9-related disorder often present with deafness, cataracts and nephropathy." (PMID 26542704, 2015). "In mice, we conclude that PodΔMyh9 predisposes to experimental nephropathy due to both Adriamycin and the Tg26 model of HIV-nephropathy, and this predisposition requires more than the loss of one Myh9 allele." (PMID 23874454, 2013). "Since HIV infection increases the risk for nephropathy by a factor of nearly fivefold, it is possible that other environmental or genetic factors interact with APOL1 and/or MYH9 to mediate risk of renal disease." (PMID 21698141, 2011). "The percentage of patients with MYH9-RD who experience kidney damage ranges from 30% to 70%." (PMID 40416435, 2025). "The MYH9 variant rs11089788 (MYH9:c.-19-5801G>T; 45.42% in gnomAD Aggregated database) was shown in one study to confer a higher risk for severe kidney disease in a cohort of patients with CFHR5 nephropathy/C3 glomerulopathy." (PMID 37761826, 2023). "Effective strategies to cure extra-hematological features of MYH9-RD, such as renin-angiotensin pathway inhibitors to slow nephropathy progression, or cochlear implantation to overcome profound deafness, have become available during the last decade for patients at risk for these complications." (PMID 32079152, 2020). "At the same time ischemia was already identified as a second hit injury that reveals the effect of MYH9 nephrogenic variants on GFR attrition, as in risk SNPs carriers with sickle cell anaemia, severe kidney ischemia triggered and enhanced secondary nephropathy." (PMID 32873246, 2020). "In addition, some inherited kidney diseases, such as myosin heavy chain 9 (MYH9)‐related nephropathy, show clinical courses and/or pathological findings similar to those of AS and can consequently be misdiagnosed." (PMID 31364286, 2019). "Renal biopsy is not usually performed in MYH9-nephropathy because ofthe risk of bleeding, reserved for cases in which the differential diagnosis isnecessary." (PMID 29782633, 2018). "We subsequently detected p.R1165C in the MYH9 gene, which is often associated with hearing disorders but not nephropathy or cataract." (PMID 27437156, 2016). "Compelling statistical evidence in human cohorts points to the G1 and G2 alleles of APOL1, rather than MYH9 variation, as the most likely contributors to nephropathy risk." (PMID 26147622, 2015). "In a previous report, investigators found that loss of Myh9 did not predispose mice to Tg26-nephropathy, but our results are not contradictory." (PMID 23874454, 2013). "Stratified analyses based on the chromosome 22 nephropathy risk haplotypes demonstrated that FRMD3 variants were associated with diabetic nephropathy risk in cases without two MYH9 (or APOL1) risk haplotypes." (PMID 21698141, 2011). "In addition to the nephropathy risk imparted by APOL1 G1 and G2 variants, our results support residual nephropathy risk residing within MYH9, or other c22 variants in linkage disequilibrium with the MYH9 E1 haplotype." (PMID 21698141, 2011).
Nephropathy (continued). "Our analyses in 3263 AA T2DM-ESRD cases and non-diabetic, non-nephropathy controls revealed an approximate 25–30% increase in DN risk with multiple FRMD3 SNPs in subjects not homozygous for the MYH9 E1 risk haplotype (or APOL1 risk variants)." (PMID 21698141, 2011). "We conclude that variants in FRMD3 contribute to the risk for nephropathy in AA with T2DM, an effect that was observed only after accounting for MYH9 (and less so APOL1) gene variants and evaluating a subset of AA cases likely enriched for T2DM-associated nephropathy." (PMID 21698141, 2011). "However, NMIIA directs convergence and extension tissue movements during the development of the kidney tubules, accounting for nephropathy in some MYH9-RD cases, characterized by altered NMIIA localization in renal structures and reduced NMIIA expression in podocytes." (PMID 26542704, 2015). "Although recent studies have provided statistical evidence implicating APOL1 variation in nondiabetic nephropathies, MYH9 risk variants are still associated with chronic kidney disease (CKD) in non-African American populations and in sickle cell disease nephropathy." (PMID 26147622, 2015). "Markers in FRMD3, a gene associated with type 1 diabetic nephropathy in Caucasians, appeared to interact with MYH9; however, increased nephropathy risk was seen in diabetic cases lacking two MYH9 risk haplotypes, and protective effects were seen in those with two MYH9 risk haplotypes." (PMID 21698141, 2011). "Thus,MYH9-nephropathy may result from an alteration in the podocytecytoskeleton." (PMID 29782633, 2018). "We observed a significant decrease in myh9 expression when zebrafish embryos were injected with the proposed dominant-negative APOL1 G2 allele alone (21% reduction; p = 0.043), suggesting that the mutant protein may be suppressing myh9, either directly or indirectly, to induce nephropathy." (PMID 26147622, 2015). "In addition, relationships between APOL1 G1/G2 nephropathy risk variants and non-muscle MYH9 risk variants (E1 risk haplotype) and SCT were assessed to determine whether interactions between these genes were present." (PMID 26592908, 2015). "A GWAS in 1,000 diabetic African Americans with ESRD in comparison with 500 nondiabetic cases and 500 non‐nephropathy controls demonstrated that 16 SNPs in pooled DNA were associated with nondiabetic ESRD and 12 of these SNPs are in or near the MYH9 gene." (PMID 33377622, 2021). "MYH9 and APOL1 are strongly associated with non-diabetic ESRD in AAs and can potentially limit ability to detect other nephropathy susceptibility genes with weaker effect." (PMID 21698141, 2011). "The patients with MYH9-RD may also display nonhematologic manifestations, including sensorineural deafness, nephropathy, and cataracts." (PMID 31977897, 2020). "Polymorphisms in myosin heavy chain 9 (MYH9) gene on chromosome 22 have been shown to be associated with a risk for focal segmental glomerulosclerosis (FSGS), HIV-associated nephropathy CKD with admixed nondiabetic kidney disease, hypertension-associated ESRD, and nondiabetic etiologies of ESRD." (PMID 31534799, 2019). "Although the nephropathy association with MYH9 is markedly attenuated after accounting for the coding variants in APOL1, three groups observe independent MYH9 association with non-diabetic nephropathy (personal communication 2010: Jeffrey Kopp; Carl Langefeld; Linda Kao)." (PMID 21698141, 2011). "In addition, FRMD3 allele frequencies in the 513 AA with T2DM lacking nephropathy were not significantly different compared to the 1,671 non-diabetic, non-nephropathy controls, whether or not stratified on MYH9 E1 haplotype homozygosity (all p-values>6E−1)." (PMID 21698141, 2011). "We also observed a significant increase in myh9 expression in APOL1 G1/atpif1α-MO vs. APOL1 G1 injected embryos, however, neither of these conditions induced nephropathy." (PMID 26147622, 2015).
Epstein syndrome (29 papers, 2006 to 2026). "Genetic testing identified a rare MYH9 variant (p.I1816V), previously reported in association with Epstein syndrome." (PMID 41243005, 2025). "As a result of these findings, we suspected that this case of Fechtner syndrome due to a MYH9 mutation was de novo." (PMID 31977897, 2020). "Mutation in the gene that encodes for MYH9 is found to be responsible for Fechtner's syndrome, and in addition, MYH9 has been identified in urine samples." (PMID 24327929, 2013). "Background/Objectives: MYH9 gene variants cause MYH9-related disease (MYH9-RD), which is also known as Epstein syndrome, Fechtner syndrome, May-Hegglin anomaly, and Sebastian syndrome." (PMID 41751538, 2026). "MYH9-RD is a collection of disorders caused by mutations in the MYH9 gene, encoding the Myosin9 subunit of Myosin2A, which includes May-Hegglin anomaly, Sebastian syndrome, Fechtner syndrome, and Epstein syndrome." (PMID 40589526, 2025). "Here, we studied the function and structure of platelets in three family members with a heterozygous mutation R1933X in the MYH9 gene, characteristic of closely related disorders known as the May-Hegglin anomaly and Sebastian syndrome." (PMID 36404341, 2022). "Prior to the identification of the underlying molecular cause, individuals with MYH9-related disease were variously diagnosed as having Epstein syndrome, Fechtner syndrome, May-Hegglin anomaly or Sebastian syndrome." (PMID 29853544, 2018). "In humans, mutations in MYH9 result in MYH9-related disorders, including May-Hegglin anomaly, Fechtner syndrome and Sebastian syndrome." (PMID 26542704, 2015). "Giant platelets associated with neutrophil inclusions will orient toward MYH9-related diseases (May-Hegglin, Sebastian, Fechtner, and Epstein syndromes)." (PMID 17109744, 2006). "As a MYH9 disorder, Fechtner syndrome is characterized by nephritis, giant platelets, granulocyte inclusion bodies (Döhle-like bodies), cataract, and sensorineural deafness." (PMID 31885961, 2019). "More than 45 mutations are identified in MYH9 to date and some of them are linked to a large number of autosomal-dominant disorders including May-Hegglin anomaly, Sebastian platelet syndrome, Fetchner syndrome, Bernard-Soulier syndrome, Alport syndrome, and Epstein syndrome." (PMID 25072053, 2014). "MYH9 gene mutations result in the development of several autosomal dominant disorders, such as May-Hegglin anomaly (MHA) and Epstein syndrome (EPS)." (PMID 39273383, 2024). "For example, these large platelets are characteristic of May–Hegglin anomaly, Fechtner syndrome, Sebastian syndrome, and Epstein syndrome, which are considered MYH9-related genetic diseases." (PMID 37398659, 2023). "These rare autosomal dominant disorders are known as MYH9-related disorders (MYH9-RDs), and encompass May-Hegglin anomaly, Sebastian, Fechtner, and Epstein syndromes." (PMID 35125114, 2022). "MYH9-related disorders were initially described as four syndromes, May–Hegglin anomaly, Fechtner syndrome, Sebastian syndrome, and Epstein syndrome." (PMID 31977897, 2020). "However, knock-in mice, in which one Myh9 allele has been modified to contain a specific dominant pathogenic Myh9 mutation, R702C, develop defects, including hearing loss and kidney disease, that are similar to symptoms associated with several MYH9-related syndromes such as May-Hegglin anomaly." (PMID 29853544, 2018). "In humans, mutations in MYH9 gene, which encodes the heavy chain, lead to autosomal dominant diseases collectively known as MYH9-related diseases (MYH9-RDs), which include May–Hegglin Anomaly, Sebastian Syndrome, Fechtner Syndrome, and Epstein Syndromes." (PMID 24478771, 2014). "Autosomal-dominant giant platelet syndromes (Fechtner, Sebastian platelet syndrome, Epstein, and May-Hegglin anomaly) display a broad spectrum of phenotypes, resulting from the different mutations in the nonmuscle myosin heavy chain 9 gene (MYH9)." (PMID 34063320, 2021).
Epstein syndrome (continued). "MYH9-RD results in a plethora of syndromes, such as May–Hegglin anomaly (MHA), Sebastian syndrome (SBS), Fechtner syndrome (FTNS), and Epstein syndrome (EPS)." (PMID 39273383, 2024). "Recently, it has been shown that mutations in MYH9, the gene encoding for nonmuscle myosin heavy chain IIA (NMMHC-IIA), are responsible for Fechtner syndrome, Epstein syndrome, and other two MTCPs (Sebastian syndrome and May-Hegglin anomaly) without renal, ocular, or hearing defects." (PMID 21904677, 2011).
chronic kidney disease (27 papers, 2010 to 2026). Impairment of the renal function secondary to chronic kidney damage persisting for three or more months. "Defects in this gene can cause many diseases, such as MYH9-related diseases (MYH9-RD), chronic kidney disease, and sensorineural deafness." (PMID 36374212, 2022). "MYH9 missense mutations have been shown to cause an autosomal-dominant disorder, termed MYH9-related disease (MYH9-RD), and associated with other human diseases such as chronic kidney disease, non-syndromic deafness, and cancer." (PMID 32094322, 2020). "MYH9 gene polymorphisms were associated with chronic kidney disease in genome wide association studies (GWAS) of Hispanic and European Americans." (PMID 32873246, 2020). "Although MYH9-related diseaseis a rare cause of glomerulopathy and end-stage renal disease, awareness of raregenetic kidney disorders is essential to ensure accurate diagnosis and propermanagement of orphan disease patients." (PMID 29782633, 2018). "The result from a cohort study on chronic kidney disease (CKD) in Saudi Arabian populations showed that rs4821480 in MYH9 was significantly associated with an increased risk of development of CKD." (PMID 37391705, 2023). "MYH9 has been reported to be involved in various human diseases, including chronic kidney disease, non-syndromic deafness, and tumor." (PMID 34743203, 2022). "Despite its established association with chronic kidney disease (CKD) the role of myosin-9 (MYH9) gene variation on transplanted kidney function remains unknown." (PMID 32873246, 2020). "SNPs in the MYH9 and APOLI genes associated with increased risk of chronic kidney disease have been found in association with albuminuria in SCD patients." (PMID 30410998, 2018). "MYH9, one of the top-ranked genes with differential APA usage, has been previously demonstrated to be associated with end-stage renal disease in African Americans." (PMID 28984183, 2017). "The characterization of the associations between chronic kidney diseases (CKD) and polymorphisms on chromosome 22q12, namely MYH9 and APOL1 was an immense breakthrough for population-based genetic studies of CKD." (PMID 23285077, 2012). "Stratifin promotes renal fibrosis via binding with MYH9 in chronic kidney disease." (PMID 40416435, 2025). "As expected, MYH9, for which genetic variants were found to be associated with non-diabetic end-stage renal disease, is missing in these lists as it encodes a non-muscle myosin chain." (PMID 20634963, 2010). "Secondly, it has demonstrated that the associated MYH9 risk occurs at an early stage and is likely more pronounced in subjects with type 2 diabetes unlike previous studies which have shown a stronger association with nondiabetic end-stage renal disease." (PMID 23285077, 2012). "Firstly, it has shown that polymorphisms within the MYH9 are associated with early changes in kidney function and urinary albumin excretion in a community based cohort as opposed to a patient population with clinically overt chronic kidney disease." (PMID 23285077, 2012). "Though single nucleotide polymorphisms (SNPs) in the non-muscle myosin gene (MYH9) have been reported to explain most of the excess risk of nondiabetic chronic kidney disease (CKD), in African-Americans, some studies have also shown associations with diabetic end-stage renal disease." (PMID 23285077, 2012). "Polymorphisms in the non-muscle heavy chain 9 (MYH9) gene have been associated to the risk of chronic kidney disease (CKD) in populations with non-diabetic kidney disease, HIVAN, and idiopathic FSGS." (PMID 24658608, 2014). "In this study, we report the findings from a case/control association analysis of non-diabetic chronic kidney disease and variants in APOL1 and MYH9 genes in an African sample from southwest Nigeria." (PMID 22956460, 2013).
chronic kidney disease (continued). "Single nucleotide polymorphisms (SNPs) in MYH9 and APOL1 on chromosome 22 (c22) are powerfully associated with non-diabetic end-stage renal disease (ESRD) in African Americans (AAs)." (PMID 21698141, 2011). "Genetic variants in MYH9 are associated with non-diabetic chronic kidney disease, FSGS and HIV nephropathy, however whether the association is due to a functional variant in MYH9 or due to LD with nearby Apolipoprotein L1 (APOL1) remains a point of controversy." (PMID 29665793, 2018). "Despite growing evidence of the expression of NMMHC-IIA in the kidney tissue, as well as its important function in podocytes cytoskeletal organization, cell adhesion, traction and motility, the role of MYH9 variation in the pathogenesis of chronic kidney disease (CKD) remains unclear." (PMID 32873246, 2020).